IRAK1 (interleukin 1 receptor associated kinase 1)
Diseases named in the same sentence as IRAK1 in open-access papers (continued):
Sharing a sentence is not in itself a finding about the gene and the disease.
cancer (continued). "The results indicated that strong positive relationships with PD-L1(CD274) and IRAK1 gene expression in diverse cancer types of TCGA." (PMID 35669566, 2022). "To conclude, more specific and clinical samples are necessary to identify the benefits of anti-IRAK1 in cancer survival." (PMID 35669566, 2022). "We further explored the potential relationship between PD-L1 (CD274) and IRAK1 gene expression in diverse cancer types of TCGA." (PMID 35669566, 2022). "We found that IRAK1 is related to immune pathways, including the PD-L1 and PD-1 checkpoint pathway in cancer." (PMID 35669566, 2022). "And the result of the enrichment analysis suggested that IRAK1 related to immune checkpoint pathway in cancer." (PMID 35669566, 2022). "We then presented the genetic alteration of IRAK1 across all cancer types in the TCGA cohort, depicting that the most frequent alteration was amplification." (PMID 35669566, 2022). "Then, we evaluated the effect of IRAK1 inhibitor pacritinib on the growth and proliferation of different cancer lines by the MTT assay, including MDA-MB-231, U251, Hep3B, Kyse30, and A498." (PMID 35669566, 2022). "And pacritinib upregulated PD-L1 expression in several cancer cell lines, which indicating that IRAK1 can be used as a reliable marker to predict the efficacy of immunotherapy." (PMID 35669566, 2022). "Given the potential role of IRAK1 in tumorigenesis, it is essential to conduct a pan-cancer analysis of it." (PMID 35669566, 2022). "IRAK1 inhibitor pacritinib inhibit proliferation and upregulate PD-L1 expression in different cancer cell lines." (PMID 35669566, 2022). "In the TCGA pan-cancer cohort, IRAK1 expression positively correlated with DKC1 (R = 0.54), FAM58A (R = 0.51), NAA10 (R = 0.54), SLC10A3 (R = 0.55), and UBLA4 (R = 0.62)." (PMID 35669566, 2022). "The results revealed that IRAK1 expression negatively correlated with T cell CD8+ in seven cancer types, but a positive relationship in UVM." (PMID 35669566, 2022). "Immunohistochemistry experiments confirmed a higher positive rate of IRAK1 in carcinoma than in para-carcinoma tissues (χ2 = 18.006, p < 0.001)." (PMID 36421353, 2022). "These were further confirmed by the immunohistochemistry results that the carcinoma tissues presented a higher positive expression rate of IRAK1 than para-carcinoma tissues." (PMID 36421353, 2022). "Recent studies have revealed that IRAK1 is involved not only in inflammatory diseases but also in progression of several cancers." (PMID 34576039, 2021). "IRAK1 enhances cancer stemness and weakens the sensitivity to doxorubicin and sorafenib using the AP-1/AKR1B10 axis in HCC." (PMID 34621787, 2021). "Kinase activity is essential for IRAK1 signaling in response to RT in all settings tested, both in zebrafish embryos and human cancer cells." (PMID 31799178, 2019). "In order to delineate the role of miR-146b in EMT by augmenting PTC cancer cell migration/invasion, we identified a regulatory mechanism linking miR-146b and its target gene IRAK1 in PTC cell lines." (PMID 28294980, 2017). "The IRAK family members are mediators of TLR/IL1R signal pathways, and amounts of evidence implicate that these kinases including IRAK1 are vital cancer targets." (PMID 27619757, 2016). "We next sought to determine the effect of IRAK1 knockdown on aggressive growth properties of TNBC, such as three-dimensional cultures associated with invasive growth and cancer-initiating cells or cancer stem cells (CSCs)." (PMID 26503059, 2015). "Downstream IRAK1 signaling was suppressed through TRAF6, attenuating activation of NF-κB and MAPK and stimulating cancer cell death, thus highlighting the potential use of IRAK1 inhibitors in the treatment of HNSCC." (PMID 26527316, 2015).
cancer (continued). "Additional evidence indicating the importance if IRAK-1 in cancer came from studies of microRNAs (miRNAs)." (PMID 25452754, 2014). "This is especially true given that many cancers exhibit increased protein levels of IRAK-1 and IRAK-4 and are resistant to chemotherapy." (PMID 25452754, 2014). "A growing body of research indicates that interleukin-1 receptor-associated kinase 1 (IRAK-1) signaling may play a significant role in the development and progression of cancer." (PMID 41011273, 2025). "Consequently, IRAK1 is considered a promising cancer drug target and IRAK1 inhibitors have been developed and evaluated preclinically and clinically." (PMID 39451208, 2024). "The extensive research on IRAK1 has greatly enhanced our understanding of its role in cancer metastasis and therapeutic resistance, highlighting its clinical relevance as a potential biomarker, therapeutic target, or both, in various solid tumors and hematologic malignancies." (PMID 39451208, 2024). "Moreover, IRAK1 was found to be responsible for radiotherapy resistance in human cancer cells; for that reason, selective IRAK1 inhibitors were proposed for cancer treatment." (PMID 36845147, 2023). "Since IRAK1 signaling has been shown to activate the downstream NF-κB transcription factors in both immune and cancer cells, targeting IRAK1 in PCa may be an alternative and therapeutically feasible approach." (PMID 37370720, 2023). "Interestingly, IRAK1 is also overexpressed in several cancers including liver, lung, breast, and endometrium; moreover, its expression was associated with unfavorable outcomes and poor survival." (PMID 36845147, 2023). "In recent years, IRAK1 expression or alteration has been reported in several cancers." (PMID 35669566, 2022). "In addition, through GEPIA2.0, we found that IRAK1 levels were significantly different in different pathological cancer stages, including ACC, LIHC, KIRP, KIRC, THCA, and OV." (PMID 35669566, 2022). "Finally, to further explore the relationship between the treatment of IRAK1 inhibitor and PD-L1 expression in cancer, we performed a flow cytometry assay to detect PD-L1 levels in different cancer types." (PMID 35669566, 2022). "We then curated a pan-cancer analysis of IRAK1 genetic alteration." (PMID 35669566, 2022). "In addition, the combination of IRAK1 inhibitor with immunotherapy is expected to be a feasible treatment for patients with cancer with high IRAK1 expression." (PMID 35669566, 2022). "Overall, these results indicate that the level of IRAK1 in cancer which could be significant biomarker both for predicting cancer survival and immunotherapy response in ACC, KICH, BRCA, LGG, and UVM." (PMID 35669566, 2022). "In human cancer cells and a zebrafish model, IRAK1 was shown to be responsible for RT resistance." (PMID 36226067, 2022). "However, IRAK1 has been shown to have an antiapoptotic effect in cancer cells, and to contribute to developing resistance to radiotherapy as well as to paclitaxel and methotrexate treatment." (PMID 36226067, 2022). "A systematic analysis based on the cancer genome atlas (TCGA) indicated that IRAK1 was highly expressed in 18 cancer types (p < 0.01) and may be a pan-cancer biomarker." (PMID 36421353, 2022). "Recently, increasing evidence supports a potential role of IRAK1 in cancer progression." (PMID 35669566, 2022). "IRAK1 enhances cancer stemness and paclitaxel resistance in cancer." (PMID 36045397, 2022). "Our study reveals that IRAK1 can function as a prognostic marker in various malignant tumors." (PMID 35669566, 2022). "Thus, our study investigated the potential molecular and immune-related pathways of IRAK1 in various cancer types." (PMID 35669566, 2022). "In addition, immunohistochemistry was used to assess protein expression levels of IRAK1 in CRC clinical specimens, and high expression of IRAK1 were shown in cancer lesions." (PMID 34576039, 2021).
cancer (continued). "In addition, DIM inhibited cancer cell invasion by suppression of metastasis-associated protein 2 (MTA2), NF-κB, interleukin 1 receptor-associated kinase 1 (IRAK1), and epidermal growth factor receptor (EGFR) based on upregulation of miR-146a." (PMID 35582221, 2020). "The relative importance of catalytic vs. structural functionalities of IRAK1 is an important consideration for the development of IRAK1 inhibitors for clinical use, particularly in radioresistant cancer, and will be discussed in detail in the closing sections of this review." (PMID 31799178, 2019). "Further studies of whether TLR5 or IRAK-1/4 antagonists improve cancer cachexia symptoms are necessary." (PMID 30410674, 2018). "Implicating IL-1β-mediated inflammation in cancer development raises the possibility that IRAK1, upstream of IL-1β, and with a role in the NF-κB pathway via TLR/IL-1R signaling, may represent a target for cancer prevention in patients known to be at high risk." (PMID 30279971, 2018). "A number of efforts have been made to develop IRAK4 and IRAK1 inhibitors aimed at cancer treatment." (PMID 27845762, 2016). "Importantly, paclitaxel treatment induces strong IRAK1 phosphorylation, an increase in inflammatory cytokine expression, enrichment of cancer stem cells and acquired resistance to paclitaxel treatment." (PMID 26503059, 2015). "As we previously addressed, IRAK inhibitors (especially IRAK-1 and -4) may also have therapeutic applications in cancer." (PMID 25452754, 2014). "There is an increasing body of data to suggest that IRAK-1 signaling may be important to the development and progression of cancer." (PMID 25452754, 2014). "Our working hypothesis is that in cancers with reduced levels of IRAK-M but elevated levels of IRAK-1, -2, and/or -4 will show increased IRAK-4 signaling and consequently elevated levels of inflammatory molecules." (PMID 25452754, 2014). "Moreover, low IRAK1 expression can function as a prognostic marker in different cancers." (PMID 40804837, 2025). "Finally, we provide timely updates on the development of IRAK1-targeted therapy for human cancers." (PMID 39451208, 2024). "Interleukin-1 Receptor Associated Kinase 1 (IRAK1) is a serine/threonine kinase that plays a critical role as a signaling transducer of the activated Toll-like receptor (TLR)/Interleukin-1 receptor (IL-1R) signaling pathway in both immune cells and cancer cells." (PMID 39451208, 2024). "Moreover, the capacity of IRAK1 degraders to treat cancers may potentially depend on the IRAK1 scaffolding function." (PMID 38792088, 2024). "Hence, IRAK1 has become an essential protein for cell survival in many human cancer cells." (PMID 37370720, 2023). "The prognostic value of IRAK1 in most human cancers remained unknown." (PMID 35669566, 2022). "Furthermore, inhibitors of IRAK1 pacritinib upregulated PD-L1 expression in several cancer cell lines, indicating that the pharmacological inhibition of IRAK1 could be synergistic with immunotherapy in the future." (PMID 35669566, 2022). "Altogether, these results indicated that IRAK1 might play a significant role in different cancers." (PMID 35669566, 2022). "Thus, multiple mechanisms by which perturbing IRAK1 function may have beneficial effects in inflammatory diseases and cancer may be posited, and several caveats (e.g., potential deleterious consequences of inhibiting innate immune response) may be foreseen." (PMID 30279971, 2018). "We therefore expect that therapeutic targeting of IRAK1 may be particularly effective in vivo through abrogating both cancer-intrinsic and cancer-promoting immune response, although addressing this aspect will be technically challenging in immune-deficient mice." (PMID 26503059, 2015). "The expression of IRAK1 is elevated in most types of cancer, with notable exceptions in THCA and LAML, highlighting its influence on cancer progression." (PMID 39451208, 2024).
cancer (continued). "Cancer cell growth, migration, tumourigenesis and chemoresistance can all be impacted by targeting the proteins involved in the IRAK2 pathway, including IRAK1 and IRAK4." (PMID 36768848, 2023). "The clinical value of targeting IRAK gene family members, specifically IRAK1 and IRAK4, has been elucidated in several cancer types." (PMID 37108068, 2023). "The prognostic signature that we constructed consisted of seven cancer driver genes (CDKN2C, HRAS, IRAK1, LOX, MYCN, NRAS, and PABPC1)." (PMID 36017503, 2022). "We identified the top five related genes (DKC1, FAM58A, NAA10, SLC10A3, UBL4A) that mostly correlated with IRAK1 by GEPIA2.0; the heatmap displayed the correlation in pan-cancers." (PMID 35669566, 2022). "It participated in the IRAK4/IRAK1/AP-1/AKR1B10 signaling pathway and AUF1-mediated post-transcriptional regulation of AKR1B10 expression to regulate cancer stemness and drug resistance in HCC." (PMID 36246599, 2022). "Selective IRAK1 inhibitors, such as the organic JAK2/FLT3 inhibitor pacritinib and chemical compounds, such as Jh-X-119-01, are being considered for cancer treatment." (PMID 36226067, 2022). "It has been demonstrated that microRNA-146a can target many genes, such as IRAK1, IRAK2, TRAF6, RIG-I, IRF-5, STAT-1, PTC1, Numb, and WASF2, to play a variety of roles in human diseases, including cancers and inflammatory immune diseases." (PMID 31798643, 2019). "miR-125b and -146a regulate several other molecules in the NF-κB pathway and indirectly modulate NF-κB; miR-146a has been shown to down-regulate TLR signaling molecules IRAK1 and TRAF6 in cancer, with a corresponding drop in NF-κB level." (PMID 23335942, 2012). "IRAK1 plays a pivotal role as one of the two putative kinases that are responsible for converging downstream signaling of the TLR/IL-1R signaling pathways and is increasingly recognized for its involvement in aberrant TLR/IL-1R signaling in cancer biology." (PMID 39451208, 2024). "IRAK1 modulates several aspects of the TME, further facilitating cancer metastasis." (PMID 39451208, 2024). "Interestingly, we found that IRAK-1 was downregulated in the A2780 and OVCAR8 cancer cell lines after miR146a transfection." (PMID 38582949, 2024). "Collectively, these findings indicate that IRAK1 functions are not strictly dependent on its catalytic activity, underscoring its significance in cancer development and highlighting the importance of developing IRAK1 inhibitors." (PMID 39451208, 2024). "Collectively, these studies describe the involvement of IRAK1 in the activation of downstream pathways, including NF-κB and MAPKs/NLRP3/IL-1β, which promote the production of mesenchymal markers that induce a shift in the cellular phenotype of cancer cells." (PMID 39451208, 2024). "IRAK1 is a serine/threonine-protein kinase that has been involved in tumorigenesis by driving TRAF6-mediated NF-kB and p38MAPK signaling activation in numerous cancers." (PMID 37031183, 2023). "Although IRAK1 expression has been reported in several cancers to date, its amplification had not been examined before." (PMID 35669566, 2022). "Furthermore, it is reported that miR-146a can restrict the NF-κB signaling pathway mediated by IRAK1 and TRAF6, which is an important signaling factor involved in the occurrence of cancers." (PMID 33816633, 2021). "Overexpression and activation of IRAK1 and IRAK4 have been demonstrated in several types of cancer." (PMID 27504095, 2016). "Similarly, re-expression of miR-146a induced by isoflavone in pancreatic cancer was also correlated with reduced invasion and down-regulation of IRAK1 and EGFR, indicating that this molecular pathway is involved in multiple cancers." (PMID 23335942, 2012).
cancer (continued). "Both IRAK1 and IRAK4 are known to show true kinase activity and have been exclusively explored as targets in a variety of auto-immune and inflammatory diseases: rheumatoid arthritis, diabetes, and systemic lupus erythematosus, as well as in a few cancer cases in the scientific literature." (PMID 37370720, 2023). "To study a role of IRAK1 in CSCs, we assess the ability of TNBC cells to form mammospheres in serum-free suspension culture as a functional assay for CSCs22, as there is no single common marker that can be reliably used to assess the cancer stemness across these different TNBC cell lines." (PMID 26503059, 2015). "However, no immunological pan-cancer analysis of IRAK1 is available." (PMID 35669566, 2022).